TRIM56 (tripartite motif containing 56)
Diseases named in the same sentence as TRIM56 in open-access papers (continued):
Sharing a sentence is not in itself a finding about the gene and the disease.
hepatoma (5 papers, 2017 to 2025). "TRIM56 was also lower in other hepatocellular carcinoma cell lines, such as HepG2 and Huh7 cells, than in HEK293." (PMID 41472269, 2025). "The antiviral effects of TRIM56 are virus-dependent, because augmenting the expression of TRIM56 in human hepatoma (Huh7) cells did not restrict the repetition of the hepatitis C virus (HCV)." (PMID 38051999, 2023). "Although TRIM56 fails to restrict HCV replication when overexpressed in human hepatoma Huh7 cells, TRIM56 overexpression in HEK293 cells support some selectable HCV RNA replicons at very low efficiencies." (PMID 28829373, 2017).
lung adenocarcinoma (4 papers, 2022 to 2024). A carcinoma that arises from the lung and is characterized by the presence of malignant glandular epithelial cells. "The reduced expression of TRIM56 in lung adenocarcinoma is associated with poor prognosis." (PMID 36902478, 2023). "OTUD3 can also be ubiquitinated by TRIM56, thereby inhibiting invasion and migration of lung adenocarcinoma." (PMID 37829187, 2023). "Exosomal circZNF451 inhibits anti-PD1 therapy in lung adenocarcinoma by polarizing macrophages in complex with TRIM56 and FXR1." (PMID 36902478, 2023). "In lung adenocarcinoma, mir-542 and mir-627 have the potential to inhibit TRIM56 expression." (PMID 36902478, 2023). "The overexpression of TRIM56 inhibits the invasion and migration of lung adenocarcinoma cells." (PMID 36902478, 2023). "TRIM56 acts as a tumor suppressor, inhibiting the migration and invasion of lung adenocarcinoma." (PMID 37829187, 2023).
Hepatic steatosis (3 papers, 2024 to 2026). Steatosis is a term used to denote lipid accumulation within hepatocytes. "Similarly, we observed increased hepatic steatosis and lipid droplet accumulation in Trim56-HepKO mice." (PMID 38206764, 2024). "We next explored the question of whether hepatocyte-derived TRIM56 plays an important role in hepatic steatosis and NAFLD pathogenesis." (PMID 38206764, 2024). "By using unsupervised siRNA library screening of the TRIM family proteins involved in hepatic steatosis, we found that TRIM56, an established RING-type E3 ubiquitin ligase in innate antiviral immunity, was the most notable suppressor of PO-induced lipid accumulation." (PMID 38206764, 2024). "Hepatocyte TRIM56 protects against HFD-induced hepatic steatosis." (PMID 38206764, 2024). "Using unbiased protein interactomics screening and molecular validation, we found that TRIM56 directly interacted with FASN, a key lipogenesis factor driving hepatic steatosis in NAFLD/NASH." (PMID 38206764, 2024). "The TRIM56/FASN axis regulates hepatocyte lipid accumulation in Nonalcoholic liver disease and FASN inhibition protects mice against HFD-induced hepatic steatosis." (PMID 38206764, 2024).
COVID-19 (2 papers, 2021 to 2023). A disease caused by infection with severe acute respiratory syndrome coronavirus 2. "It is possible that TRIM56 gene has some polymorphisms in regulatory sequences that affect its expression in COVID-19 patients, or that SARS-CoV-2 has a genetic mutation that can facilitate the inhibition or reduction of the expression of TRIM56 gene." (PMID 38051999, 2023). "The present study aimed to determine a correlation between differential TRIM56 expression levels and severe infections of COVID-19 between the Alpha, Delta and Omicron BA.5 variants." (PMID 38051999, 2023). "Scientists looked at a protein called TRIM that helps fight viruses to see if a specific TRIM protein, TRIM56, was linked to how poorly people became with COVID-19." (PMID 38051999, 2023). "In contrast, our results showed a notable reduction in the expression of TRIM56 mRNA in severe patients compared with healthy controls and patients with mild COVID-19." (PMID 38051999, 2023). "The study looked at the blood samples of 330 patients and found that COVID-19 patients had less TRIM56 than healthy people, especially those who were particularly ill." (PMID 38051999, 2023). "The area under curve-receiver operating characteristic analysis value for TRIM56 gene expression was 0.786, implying that the expression of this gene is frequently required for the severity of COVID-19." (PMID 38051999, 2023). "Since previous studies reported that the CRP marker significantly correlated with the severity of COVID-19 as a predictor factor, we analyzed the relationship between TRIM56 mRNA level and CRP value in all patients included in this study." (PMID 38051999, 2023). "Our study provides a clue to the TRIM proteins' role in COVID-19 and focuses on expression of the TRIM56 gene in blood samples." (PMID 38051999, 2023). "The impact and antiviral mechanisms of TRIM56 gene in COVID-19 need further investigation." (PMID 38051999, 2023). "Additionally, the AUC-ROC value for TRIM56 gene expression was 0.786, implying that the expression of this gene is related to the severity of COVID-19." (PMID 38051999, 2023). "We compared also Ct values and TRIM56 mRNA levels of COVID-19 patients." (PMID 38051999, 2023). "Therefore, we evaluated the mRNA level of TRIM56 gene in our study groups of COVID-19 patients." (PMID 38051999, 2023). "TRIM56 has a restrictive role in the replication of RNA viruses like HCoV-OC43, so it is likely that TRIM56 similarly interacts with SARS-CoV-2 and as a result, the reduction of TRIM56 observed in patients with severe COVID-19 may be associated with the superior viral load in these patients." (PMID 38051999, 2023). "We evaluated whole blood samples of COVID-19 patients to assess the correlation between the severity of SARS-CoV-2 and TRIM56 expression." (PMID 38051999, 2023). "The overexpression of some of these biomarkers was similarly observed in the blood serum of severe COVID-19 patients with extrapulmonary dysfunction (e.g. SOCS3 and TRIM56)." (PMID 34262555, 2021). "Analysis of lung tissue samples of COVID-19 patients also reported a decrease in TRIM56, though this was not significant (P 0.09)." (PMID 38051999, 2023). "Moreover, qRT-PCR analysis of the whole RNA extracted from the blood serum of severe COVID-19 patients with pulmonary and extrapulmonary findings, confirmed the significant elevation in the gene expression of TRIM56 and SOCS3 in response to extrapulmonary dysfunction in severe COVID-19 patients." (PMID 34262555, 2021).
glioblastoma (2 papers, 2022 to 2023). The most malignant astrocytic tumor (WHO grade IV). "TRIM56 inhibits the radiosensitivity of human glioblastoma by regulating FOXM1-mediated DNA repair." (PMID 36902478, 2023). "TRIM56 expression is significantly increased in glioblastoma tissues and cell lines." (PMID 36902478, 2023). "Targeting TRIM56 may be an effective approach to reverse radioresistance in glioblastoma recurrence." (PMID 36902478, 2023). "TRIM56 may therefore suppress the radiosensitization of human glioblastoma by regulating FOXM1-mediated DNA repair." (PMID 36471347, 2022). "We used the study Single cell RNA-seq of adult and pediatric glioblastoma from the Single Cell Portal website to investigate which cell types within the GBM microenvironment express TRIM56 and their expression levels." (PMID 36471347, 2022). "TRIM56 has also been shown to increase FOXM1 protein levels, enhance the stability of FOXM1 by de-ubiquitination, and promote DNA damage repair through FOXM1 in glioblastoma cells." (PMID 36471347, 2022).
multiple myeloma (2 papers, 2020 to 2023). "miR-9 overexpression promotes ROS production in multiple myeloma, which targets TRIM56 and activates the NF-κB pathway to promote the development and progression of multiple myeloma." (PMID 35006436, 2020).
adenovirus infection (1 paper, 2025). "In this study, we demonstrate that TRIM56 enhances adenovirus infection by directly increasing E1A viral protein expression." (PMID 40459263, 2025).
breast tumor (1 paper, 2019). "The IHC results showed that TRIM56 is mainly localized in the cytosol in human breast tumor tissues." (PMID 31000690, 2019). "Our data showed that TRIM56 depletion by lentivirus-based shRNA decelerated breast tumor growth." (PMID 31000690, 2019).
diabetes (1 paper, 2024). "The kidney weight to body weight ratio in the STZ-Cre+/Trim56flox/flox mice was decreased compared with that in the STZ-Cre+/Trim56+/+ group at 20 weeks after induction of diabetes." (PMID 39349450, 2024). "Importantly, STZ-Cre+/Trim56flox/flox mice exhibited a notable decrease in proteinuria when compared with STZ-Cre+/Trim56+/+ mice after 8 weeks of diabetes." (PMID 39349450, 2024). "STZ-Cre+/Trim56+/+mice had lower body weight as compared with the non-diabetic counterparts after 6 weeks of diabetes, while the STZ-Cre+/Trim56flox/flox mice showed improved growth compared to STZ-Cre+/Trim56+/+ mice." (PMID 39349450, 2024).
Flavivirus Infections (1 paper, 2019). Infections with viruses of the genus FLAVIVIRUS, family FLAVIVIRIDAE. "Altogether, our study reveals TRIM56 is an RNA binding protein that acts as a ZIKV restriction factor and provides new insights into the antiviral mechanism by which this E3 ligase tackles flavivirus infections." (PMID 31251739, 2019). "Further investigations that elucidate the precise action mechanism of TRIM56 may expose therapeutic targets that can be harnessed to combat ZIKV and possibly other flavivirus infections." (PMID 31251739, 2019).
gastric cancer (1 paper, 2025). A primary or metastatic malignant neoplasm involving the stomach. "Although the inhibition of NNMT proteasomal degradation has been reported in gastric cancer, we here further characterized TRIM56 as the key E3 ubiquitin ligase for NNMT ubiquitination, and identified lysine 23 and 210 as its major ubiquitination sites." (PMID 39887931, 2025).
Hydrocephalus (1 paper, 2025). Hydrocephalus is an active distension of the ventricular system of the brain resulting from inadequate passage of CSF from its point of production within the cerebral ventricles to its point of absorption into the systemic circulation. "As expected, overexpression of TRIM56 WT notably reduced severe disease development, while overexpression of TRIM56 K110Q had a more significant impact on inhibiting hydrocephalus than that of TRIM56 WT in HSE mouse." (PMID 39747662, 2025).
Hyperglycemia (1 paper, 2024). An increased concentration of glucose in the blood. "Our study delineated that TRIM56, belongs to the C-V family, functions as an E3 ligase to catalyze the hyperglycemia-induced ubiquitination of AMPKα, thereby regulating mitochondrial biology and homeostasis to influence mtDNA leakage." (PMID 39349450, 2024). "Concomitantly, suppression of PVT1 by ASO restored the protein levels of AMPKα under hyperglycemia conditions, in contrast overexpressed TRIM56 abolished the effect of PVT1 ASO on AMPKα." (PMID 39349450, 2024). "The copy number of mtDNA released into the cytosol under hyperglycemia environment was reduced following TRIM56 siRNA treatment." (PMID 39349450, 2024). "Notably, immunoblotting analysis showed that the overexpression of TRIM56 attenuated the reno-protective effect of PVT1 ASO on mitochondrial function in the context of hyperglycemia." (PMID 39349450, 2024).
influenza (1 paper, 2024). An acute viral infection of the respiratory tract, occurring in isolated cases, in epidemics, or in pandemics; it is caused by serologically different strains of viruses (influenzaviruses) designated A, B, and C, has a 3-day incubation period, and usually lasts for 3 to 10 days. "As another example, a short C-terminal peptide derived from TRIM56 retains the anti-influenza activity is predicted to avoid the protein’s unfavorable proinflammatory property based on data from the current study." (PMID 38556084, 2024).
Insulin resistance (1 paper, 2025). Increased resistance towards insulin, that is, diminished effectiveness of insulin in reducing blood glucose levels. "Furthermore, metabolic disturbances associated with obesity, such as glucose tolerance, insulin resistance, fasting serum insulin levels, and serum lipid levels, were all markedly improved in TRIM56‐overexpressing mice." (PMID 39928840, 2025).
Kaposi's sarcoma (1 paper, 2022). A malignant neoplasm characterized by a vascular proliferation which usually contains blunt endothelial cells. "For example, in Kaposi's sarcoma, vFLIP was found to degrade SAP18 through the ubiquitin–proteasome pathway by recruiting the E3 ubiquitin ligase TRIM56." (PMID 36471347, 2022).
male infertility (1 paper, 2012). The inability of the male to effect fertilization of an ovum after a specified period of unprotected intercourse. "Functionally, FKBP6 encodes a member of FK506 binding protein family and has been associated with male infertility in humans and mice, while TRIM56 belongs to tripartite motif-containing gene family, members of which, like TRIM36 (alias HAPRIN), are involved in acrosome reaction of mammalian sperm." (PMID 23284302, 2012).
Obesity (1 paper, 2025). Accumulation of substantial excess body fat. "We believe that the elevation in TLE3 protein levels in obesity subjects is partly due to an increase at the transcriptional level, as well as a reduction in protein degradation caused by decreased TRIM56 levels." (PMID 39928840, 2025). "Collectively, our data demonstrate that overexpression of TRIM56 ameliorates diet‐induced obesity and associated metabolic abnormalities by potentiating adaptive thermogenesis." (PMID 39928840, 2025). "Based on this mechanism, we considered that augmenting TRIM56 levels in adipocytes could offer a promising therapeutic approach to ameliorate diet‐induced obesity and associated metabolic disorders." (PMID 39928840, 2025). "By integrating the findings of reduced TRIM56 expression under obesity conditions, these results highlight the unique regulatory role of TRIM56 in the progression of obesity." (PMID 39928840, 2025). "Our findings reveal that TRIM56 expression is upregulated in response to cold exposure but downregulated during obesity." (PMID 39928840, 2025). "Next, we investigated the potential of TRIM56 to alleviate diet‐induced obesity by enhancing adaptive thermogenesis." (PMID 39928840, 2025). "Conversely, in models of diet‐induced obesity, we observed a decrease in both protein and mRNA levels of TRIM56 in iWAT." (PMID 39928840, 2025). "This study pinpoints TRIM56 as a viable candidate for promoting white adipose tissue browning and as a promising therapeutic target for addressing obesity and metabolic disorders." (PMID 39928840, 2025). "Notably, the overexpression of TRIM56 in adipocytes is shown to help mice maintain a core temperature under cold conditions, as well as confer protection against diet‐induced obesity." (PMID 39928840, 2025). "Given similar food intake between the two groups, we hypothesized that the protective effects of TRIM56 against obesity are mediated through elevated metabolic rates." (PMID 39928840, 2025). "Notably, enforcing TRIM56 expression in WAT could help mice maintain body temperature in cold environments and ameliorate diet‐induced obesity, suggesting its potential as a novel target for metabolic disease management." (PMID 39928840, 2025).
overnutrition (1 paper, 2024). An imbalanced nutritional status resulting from excessive intake of nutrients. "Our data suggest that TRIM56 downregulation may thus serve as a converging point by which overnutrition and steatosis contribute to liver damage." (PMID 38206764, 2024).
Salmonella Infections (1 paper, 2017). Infections with bacteria of the genus SALMONELLA. "Indeed, we observed the appearance of ubiquitinated high molecular weight species of endogenous TRIM56 upon Salmonella infection." (PMID 28084320, 2017). "Here we provide multiple lines of evidence, which strongly support the notion that SopA-mediated ubiquitination inhibits and triggers the proteasomal degradation of TRIM56 and TRIM65 during Salmonella infection." (PMID 28084320, 2017).
steatosis (1 paper, 2024). Increased lipid within the cytoplasm of cells. "Altogether, these lines of evidence demonstrate that TRIM56 kept hepatocyte steatosis in check by interacting with FASN and conjugated K48-linked ubiquitination chains to promotes the degradation of FASN." (PMID 38206764, 2024).
ZIKV infection (1 paper, 2019). "To this end, we investigated the impact of TRIM56 on ZIKV infection in 293T-derived cells deficient in Dicer expression thus lacking the biogenesis of miRNAs." (PMID 31251739, 2019). "To assess the potential connection of TRIM56 with miRNA, we investigated the impact of TRIM56 on ZIKV infection in Dicer knockout cells that lack the biogenesis of mature miRNAs." (PMID 31251739, 2019). "We conclude from these data that TRIM56 restricts ZIKV infection by inhibiting viral RNA replication, and that such capacity depends on both its E3 ligase activity and the integrity of C-terminal portion." (PMID 31251739, 2019). "These offered tractable in vitro systems for evaluating the impact of TRIM56 on ZIKV infection in neural cells." (PMID 31251739, 2019). "To understand how TRIM56 exerts its antiviral action, we determined the domains or activities that are critical for TRIM56 to restrict ZIKV infection." (PMID 31251739, 2019). "Here, we show that host tripartite motif-containing protein 56 (TRIM56) poses a barrier to ZIKV infection in cells of neural, epithelial and fibroblast origins." (PMID 31251739, 2019). "In this study we demonstrate that TRIM56, an E3 ubiquitin ligase ubiquitously expressed in human tissues, poses a barrier to ZIKV infection in human cells." (PMID 31251739, 2019). "To investigate if TRIM56 expression changes in neural cell types following ZIKV infection, we first examined the abundance of endogenous TRIM56 protein in SVGA cells by immunoblotting." (PMID 31251739, 2019). "In this study, we demonstrate that TRIM56 exerts a direct antiviral effect on ZIKV infection in human cells of fibroblast-, epithelial-, and neural-origins and that both the E3 ligase activity and C-terminal portion of TRIM56 are critical for restricting ZIKV." (PMID 31251739, 2019). "Second, TRIM56 did not augment, but rather decreased, the minimal induction of IFNs and ISG56 late post ZIKV infection, which may be explained by TRIM56-mediated reduction in ZIKV RNA (i. e., the immune stimulus) levels." (PMID 31251739, 2019). "In addition to the Tet-inducible expression system, a constitutive overexpression strategy was also utilized to examine the impact of TRIM56 on ZIKV infection." (PMID 31251739, 2019). "Following ZIKV infection, profound reductions in ZIKV E and NS5 protein levels were observed in TRIM56-overexpressing cells as compared with control vector-transduced cells, irrespective of Dicer deficiency." (PMID 31251739, 2019). "Collectively, these data show that the deficiency of Dicer does not undermine the inhibitory effect of TRIM56 on ZIKV infection, suggesting an antiviral mechanism independent of the biogenesis of or regulation by host miRNAs." (PMID 31251739, 2019).